SIX1 (SIX homeobox 1)
Description:
Transcription factor that is involved in the regulation of cell proliferation, apoptosis and embryonic development (By similarity). Plays an important role in the development of several organs, including kidney, muscle and inner ear (By similarity). Depending on context, functions as a transcriptional repressor or activator (By similarity). Lacks an activation domain, and requires interaction with EYA family members for transcription activation. Mediates nuclear translocation of EYA1 and EYA2. Binds the 5'-TCA[AG][AG]TTNC-3' motif present in the MEF3 element in the MYOG promoter and CIDEA enhancer. Regulates the expression of numerous genes, including MYC, CCND1 and EZR (By similarity). Acts as an activator of the IGFBP5 promoter, probably coactivated by EYA2 (By similarity). Repression of precursor cell proliferation in myoblasts is switched to activation through recruitment of EYA3 to the SIX1-DACH1 complex (By similarity). During myogenesis, seems to act together with EYA2 and DACH2 (By similarity). Regulates the expression of CCNA1. Promotes brown adipocyte differentiation (By similarity).
Synonyms: BOS3; DFNA23; TIP39
Tractability: PROTAC: UniProt records ubiquitination sites on it; ubiquitination databases record sites on it.
Target class: Transcription factor
Safety:
Unwanted effects reported when the protein is acted on. In parentheses: how it was acted on, where the effect was seen, and who reports it.
Increased, adenosquamous carcinomas of endometrium (source: AOP-Wiki)
Gene: Protein-coding gene on chromosome 14 (60,643,421 to 60,658,259, reverse strand). Ensembl gene ENSG00000126778.
Subcellular location: Nucleus; Cytoplasm
Subcellular location (Human Protein Atlas): Nucleoplasm; Nucleoli
Pathways (Reactome):
Developmental Biology: Formation of the ureteric bud
Gene Ontology:
Molecular function: DNA binding; DNA-binding transcription activator activity, RNA polymerase II-specific; DNA-binding transcription factor activity; protein binding; RNA polymerase II cis-regulatory region sequence-specific DNA binding; sequence-specific DNA binding; sequence-specific double-stranded DNA binding; transcription cis-regulatory region binding; DNA-binding transcription factor activity, RNA polymerase II-specific; chromatin binding; transcription coactivator binding
Biological process: positive regulation of DNA-templated transcription; positive regulation of transcription by RNA polymerase II; protein localization to nucleus; branching involved in ureteric bud morphogenesis; embryonic cranial skeleton morphogenesis; embryonic skeletal system morphogenesis; epithelial cell differentiation; generation of neurons; inner ear development; inner ear morphogenesis; kidney development; mesonephric tubule formation; metanephric mesenchyme development; myoblast migration; negative regulation of neuron apoptotic process; organ induction; pattern specification process; positive regulation of branching involved in ureteric bud morphogenesis; positive regulation of brown fat cell differentiation; positive regulation of ureteric bud formation; regulation of branch elongation involved in ureteric bud branching; regulation of DNA-templated transcription; regulation of neuron differentiation; regulation of transcription by RNA polymerase II; skeletal muscle tissue development; and 19 more
Cellular component: nucleolus; nucleoplasm; nucleus; chromatin; transcription regulator complex; cytoplasm
Genetic constraint (gnomAD): Loss-of-function variants: 11 observed, 26.3 expected, observed/expected ratio (o/e) 0.42, 90% interval 0.26 to 0.69. The upper end of that interval is the gene's LOEUF score, 0.69, which puts it in group 2 of 6, group 1 being the genes least tolerant of losing a copy. Missense variants: 333 observed, 388.52 expected, observed/expected ratio (o/e) 0.86, 90% interval 0.78 to 0.94. Synonymous variants: 177 observed, 175.14 expected, observed/expected ratio (o/e) 1.01, 90% interval 0.89 to 1.14.
Gene-disease validity (ClinGen):
ClinGen rates the evidence that SIX1 causes each of these diseases.
branchio-oto-renal syndrome (autosomal dominant): Definitive.
Cancer hallmarks: invasion and metastasis (promotes); change of cellular energetics (promotes); genome instability and mutations (promotes); proliferative signalling (promotes); escaping programmed cell death (promotes); angiogenesis (promotes); cell replicative immortality (promotes)
Homologues: Orthologues: chimpanzee SIX1 (100% identical), dog SIX1 (99% identical), macaque SIX1 (99% identical), mouse Six1 (99% identical), pig SIX1 (99% identical), rabbit SIX1 (99% identical), rat Six1 (99% identical), guinea pig SIX1 (99% identical), tropical clawed frog six1 (94% identical), zebrafish six1b (92% identical), zebrafish six1a (86% identical), Drosophila melanogaster so (64% identical). Paralogues in human: SIX2 (77% identical), SIX4 (53% identical), SIX3 (47% identical), SIX6 (46% identical), SIX5 (45% identical), ANHX (25% identical).
Diseases named in the same sentence as SIX1 in open-access papers:
SIX1 is named in the same sentence as 152 diseases in open-access papers, as found by Europe PMC text mining. Sharing a sentence is not in itself a finding about the gene and the disease. The quoted sentences say what the papers report.
breast cancer (64 papers, 2006 to 2025). A primary or metastatic malignant neoplasm involving the breast. "A noteworthy aspect of our research lies in the utilization of the previously unexplored TNBC cell line 66cl4 as a novel model for examining the mechanisms underlying SIX1's actions in breast cancer." (PMID 38031089, 2023). "In our study, we discovered a positive association between SIX1 expression and tumor ploidy in breast cancer." (PMID 38031089, 2023). "Our findings indicate that SIX1 mRNA expression is upregulated in patients with breast cancer and is associated with different subtypes of the disease." (PMID 38031089, 2023). "Survival analyses demonstrated that DACH1 was a favorable factor while EYA2 and SIX1 were risk factors for breast cancer patients." (PMID 32550045, 2020). "High levels of Six1 are associated with adverse outcomes in luminal breast cancers, particularly the luminal B subtype." (PMID 22765220, 2012). "Herein we demonstrate for the first time that Six1 expression predicts poor prognosis, specifically in luminal subtypes of breast cancer where it is associated with the CSC population." (PMID 22765220, 2012). "Additionally, our study found that amplification of mRNA expression or mutations account for most alterations in SIX1 during breast cancer tumorigenesis." (PMID 38031089, 2023). "A significant association between SIX1 expression and OS in breast cancer patients was observed." (PMID 38031089, 2023). "In this study, we employed diverse databases to investigate changes in gene expression, prognostic significance, ploidy variations, immune infiltration, gene alteration landscape, interacting genes, and altered signaling pathways associated with SIX1 during breast cancer tumorigenesis." (PMID 38031089, 2023). "Generally, both EYA2 and SIX1 were risk factors for prognosis of breast cancer patients." (PMID 32550045, 2020). "Based on our results, histological grade of breast cancer tended to be positively associated with the mRNA expression of SIX1–3, which may indicate that high SIX1–3 levels were linked to poor differentiation." (PMID 27399099, 2016). "There is no significant publication bias for the following analysis: mRNA expression of SIX family members: breast cancer risk: SIX1: Begg test P = 0.707, Egger test P = 0.568; SIX3: Begg test P = 0.734, Egger test P = 0.474; SIX4: Begg test P = 0.707, Egger test P = 0.381." (PMID 27399099, 2016). "For example, SIX1 induces epithelial-to-mesenchymal transition (EMT) in breast cancer cells by activating transcription of the gene encoding the TGF-β type I receptor and promotes metastasis of rhabdomyosarcoma by inducing expression of the cytoskeletal protein ezrin." (PMID 25023983, 2014). "Consequently, it is crucial to determine whether SIX1 can also regulate CSCs in other subtypes of breast cancer and elucidate the underlying mechanisms involved." (PMID 38031089, 2023). "Furthermore, within this large dataset, we found that Six1 correlates with shortened relapse free survival when examining all breast cancers, but that this correlation is caused primarily by the effect of Six1 in the luminal breast cancer subtypes, particularly the luminal B subtype." (PMID 22765220, 2012). "The upper band of SIX1 disappeared when whole cell lysates from ZR75-1 breast cancer cells, HepG2 liver cancer cells and embryonic kidney HEK293T cells were treated with λ protein phosphatase, suggesting that SIX1 can be phosphorylated." (PMID 39617783, 2024). "Us and another group have shown that SIX1, a transcriptional factor that mediates embryo development, is reactivated and promotes the progression of various cancers, including PCa, breast cancer and hepatocellular carcinoma, etc.." (PMID 39623295, 2024). "Noticeably, both Six1 and Eya have been exerted to regulate breast cancer metastasis in an independent manner." (PMID 38372877, 2024).
breast cancer (continued). "Interrelation of the changes of the expression of SIX1 mRNA with the clinicopathological parameters and the clinical prognosis of the breast cancer patients." (PMID 38031089, 2023). "Taken together, these findings demonstrate that SIX1 positively modulates breast cancer stem cells at a phenotypic level, implicating its potential as a therapeutic target in breast cancer treatment." (PMID 38031089, 2023). "To gain a comprehensive understanding of SIX1 expression across various tissues and its correlation with clinicopathological features in breast cancer patients, we utilized an online database." (PMID 38031089, 2023). "Altogether, our results suggest that SIX1 plays an essential regulatory role in breast cancer's occurrence, and its amplification can be utilized as a diagnostic and prognostic predictor." (PMID 38031089, 2023). "Further investigation is required to explore alternate modes of regulating breast cancer stem cells by SIX1." (PMID 38031089, 2023). "Compared to the normal group, all four major breast cancer subtypes exhibited increased expression of SIX1, with the luminal B subtype showing the most significant increase." (PMID 38031089, 2023). "Through a combination of in vitro and in vivo experiments, we validated the regulatory role of SIX1 in promoting the growth of breast cancer stem cells (BCSCs)." (PMID 38031089, 2023). "Breast cancer data from TCGA was downloaded and screened for differentially expressed genes between high and low SIX1 expression groups." (PMID 38031089, 2023). "This suggests that SIX1 is closely involved in polyploidy and chromosomal instability in breast cancer, further enhancing our understanding of its role in disease development." (PMID 38031089, 2023). "Significant up-regulation of SIX1 was observed in 28 tumors, including breast cancer (Tumor: 2.62 ± 2.27, Normal:1.05 ± 1.77, P = 2.8e−29), while down-regulation was noted in 2 tumors." (PMID 38031089, 2023). "SIX1 showed a significant positive correlation with breast cancer stem cell markers such as ALDH1A1, EPCAM, ITGB1, and SOX2." (PMID 38031089, 2023). "Six1 promoted breast cancer metastasis in mouse models through Six1/Eya interaction, which ED mediated." (PMID 37156847, 2023). "Our findings demonstrated that the expression of SIX1 varies among different subtypes of breast cancer and that it upregulates breast cancer grading and lymph node metastasis." (PMID 38031089, 2023). "We also examined the difference in SIX1 expression among different histology subtypes of breast cancer." (PMID 38031089, 2023). "Previous studies have shown that SIX1, a transcription factor, enhances the expansion of phenotypic and functional CSCs in breast cancer, colorectal cancer esophageal cancer and phenotypic CSCs in pancreatic cancers." (PMID 38031089, 2023). "Studies have shown that the increased expression of SIX1 in tumors, such as in hepatocellular carcinoma, breast cancer, and colorectal cancer, often indicates poor clinical outcomes and promotes tumor proliferation, invasion, and metastasis." (PMID 36937004, 2023). "Patients with high SIX1 expression in all four subtypes of breast cancer had a worse prognosis compared to those with low SIX1 expression." (PMID 38031089, 2023). "This suggests that SIX1 is closely related to polyploidy and chromosomal instability in breast cancer." (PMID 38031089, 2023). "To further validate the impact of SIX1 on breast cancer stem cells and ensure the integrity and reliability of our experiments, we utilized two cell lines: murine breast cancer cell line 66cl4 and human breast cancer cell line MCF-7." (PMID 38031089, 2023). "In this study, our investigations, encompassing both in vitro and in vivo experiments, have substantiated the regulatory capacity of SIX1 on breast cancer stem cells." (PMID 38031089, 2023). "SIX1, an important downstream regulator of the signal pathway, is critical to understand the occurrence of breast cancer." (PMID 38031089, 2023).
breast cancer (continued). "We have presented evidence demonstrating the impact of SIX1 on the self-renewal and proliferation abilities of breast cancer cells in vitro." (PMID 38031089, 2023). "Recent studies have shown that SIX1 is also involved in the etiology of various cancers, such as breast cancer, pancreatic cancer, prostate cancer, and ovarian cancer." (PMID 38031089, 2023). "To further confirm the role of Six1 in enhancing the stemness of breast cancer cells, we injected different amounts of 66cl4-SCR-luc, 66cl4-shSix1 KD1-luc, and 66cl4-shSix1 KD2-luc cells to assess their tumorigenic ability." (PMID 38031089, 2023). "Recent research has focused on the relationship and mechanism of SIX1 in regulating breast cancer stem cells." (PMID 38031089, 2023). "Upregulation of SIX1 can confer paclitaxel resistance in breast cancer, DDP resistance in NSCLC, and 5-fluorouracil resistance in hepatocellular cancer." (PMID 35287543, 2022). "It has been reported that cyclin A1 and cyclin D1 were transcriptional targets of SIX1 and that SIX1 promoted cell proliferation in breast cancer by increasing cyclin A1 expression and in pancreatic cancer via increasing cyclin D1 expression." (PMID 35287543, 2022). "SIX1 has been reported to promote the proliferation and metastasis of a variety of cancer cells such as breast cancer, hepatocellular carcinoma, and GC cells." (PMID 35458126, 2022). "One approach has already been demonstrated in a breast cancer model where a small molecule inhibited the interaction between SIX1 and EYA2, reducing downstream TGF-β signaling and EMT leading to reduced metastasis in mouse xenografts." (PMID 34490256, 2021). "For example, SIX1 overexpression in breast cancer cell lines activated TGF-β signaling and activity of both factors correlated with poor prognosis in breast cancer." (PMID 34490256, 2021). "“The miR-106b-25 cluster targets Smad7, activates TGF-β signaling, and induces EMT and tumor initiating cell characteristics downstream of Six1 in human breast cancer” was the top highly cited article with 188 citations." (PMID 35252215, 2021). "SIX2, like SIX1, overexpression was detected in breast cancer and appeared to promote increased survival, self-renewal, and metastasis of tumor cells." (PMID 34490256, 2021). "For example, SIX1 can promote the growth of breast cancer by enhancing the expression of multiple glycolytic genes; it is also considered a good predictor of breast cancer prognosis." (PMID 33315534, 2021). "In the meanwhile, SIX1 was remarkably upregulated in breast cancers while EYA2 level was increased in Basal-like and Her-2 enriched subtypes." (PMID 32550045, 2020). "As an oncogene, Six1 is overexpressed in colorectal cancer, breast cancer, pancreatic cancer and squamous cell carcinoma of the oesophagus and is associated with the growth, advancement and prognosis of multiple tumours." (PMID 32220051, 2020). "These miRNAs can also target the TGF-β inhibitor Smad7 to activate the TGF-β signalling and induce EMT and tumour initiating cell characteristics downstream of Six1 in human breast cancer." (PMID 31728016, 2020). "In breast cancer, SIX1 overexpression reinstates an embryonic pathway of proliferation by upregulating cyclin A121 and mediates resistance to paclitaxel in breast cancer cells." (PMID 32258386, 2020). "Eventually, we utilized DACH1 (HR = 0.758, P = 0.083), SIX1 (HR = 1.365, P = 0.036), as well as other previously verified molecular factors to construct a predictive model for potential relapse of breast cancer patients." (PMID 32550045, 2020). "The following survival analyses showed DACH1, EYA2, and SIX1 were predictive biomarkers of prognosis of breast cancer patients." (PMID 32550045, 2020). "Our previous meta-analysis showed that increased SIX1 was closely related to poor prognosis of breast cancer patients." (PMID 32550045, 2020).